ENSG00000257178 (novel transcript, sense intronic to HOXB3)
Gene: Long non-coding RNA gene on chromosome 17 (48,579,630 to 48,582,259, reverse strand). Ensembl gene ENSG00000257178.
Gene Ontology:
Biological process: miRNA-mediated post-transcriptional gene silencing
Cellular component: RISC complex